CCDC142 (coiled-coil domain containing 142)
Synonyms: FLJ14397
Tractability: PROTAC: ubiquitination databases record sites on it.
Gene: Protein-coding gene on chromosome 2 (74,471,986 to 74,483,408, reverse strand). Ensembl gene ENSG00000135637.
Genetic constraint (gnomAD): Loss-of-function variants: 67 observed, 84.12 expected, observed/expected ratio (o/e) 0.8, 90% interval 0.65 to 0.98. The upper end of that interval is the gene's LOEUF score, 0.98, which puts it in group 4 of 6, group 1 being the genes least tolerant of losing a copy. Missense variants: 903 observed, 974.24 expected, observed/expected ratio (o/e) 0.93, 90% interval 0.88 to 0.98. Synonymous variants: 420 observed, 436.02 expected, observed/expected ratio (o/e) 0.96, 90% interval 0.89 to 1.04.
Homologues: Orthologues: chimpanzee CCDC142 (99% identical), macaque CCDC142 (95% identical), pig CCDC142 (78% identical), dog CCDC142 (78% identical), rabbit CCDC142 (77% identical), guinea pig CCDC142 (73% identical), mouse Ccdc142 (71% identical), rat Ccdc142 (71% identical), zebrafish ccdc142 (28% identical), Drosophila melanogaster CG13842 (15% identical).